TLR7 (toll like receptor 7)
Diseases named in the same sentence as TLR7 in open-access papers (continued):
Sharing a sentence is not in itself a finding about the gene and the disease.
hemorrhage (1 paper, 2023). Loss of blood from the vascular compartment to the exterior or into nonvascular body space as a result of rupture or severance of the blood vessels. "Such TLR7 activation rapidly induced gastrointestinal hemorrhage and illness in mice, confirming that activation of other TLRs could drive pathology independently of TLR4-signaling." (PMID 35871233, 2023).
hemorrhagic fever (1 paper, 2015). An infectious disease caused by certain viruses or bacteria that can damage the walls of tiny blood vessels, making them leak, and can hamper the blood's ability to clot and cause severe, life-threatening illness. "SNPs significantly associated with eye disease included three different polymorphisms TLR8 and hemorrhagic fever symptoms associated with TLR3, TLR7, TLR8 and MyD88." (PMID 25756647, 2015).
Hepatic steatosis (1 paper, 2025). Steatosis is a term used to denote lipid accumulation within hepatocytes. "Conversely, TLR7 knockout or TLR7 antagonist treatment restores Tregs proportions, mitigates intrahepatic inflammation, and reduces hepatic steatosis." (PMID 41394841, 2025).
herpesvirus infection (1 paper, 2020). "Of these, TLR3, TLR7, TLR8, and TLR9 contribute to antiviral immunity: TLR3 binds to double-stranded viral RNA; TLR7 and 8 detect single-stranded RNA viruses; and TLR9, which recognizes unmethylated cytosine-guanine (CpG) motifs in bacterial genomes, can also respond to herpesvirus infection." (PMID 33101294, 2020).
hookworm infection (1 paper, 2024). "Given the short half-life of pDC26, the reduced cytokine production after in vitro TLR-7/8 stimulation might indicate perpetual modulation of pDC by the ongoing hookworm infection." (PMID 39013877, 2024).
hyperreactivity (1 paper, 2023). "Strikingly, the absence of TLR7 prevented RSV-infected mice from developing chronic airway hyperreactivity." (PMID 37795093, 2023).
hypothyroidism (1 paper, 2019). Abnormally low levels of thyroid hormone.
IgG4-related disease (1 paper, 2025). "In IgG4-related disease, TLR7+ CD163+ M2 Mφs directly drive fibrosis by secreting TGF-β and other profibrotic factors via the TLR7/IRAK4/NF-κB pathway." (PMID 41164198, 2025). "In IgG4-related disease (IgG4-RD), CD163+ M2 Mφs promote fibroblast activation and fibrosis by releasing profibrotic cytokines (e.g., IL-33, TGF-β) through the TLR7/IRAK4/NF-κB pathway." (PMID 41164198, 2025).
infectious skin diseases (1 paper, 2012). "Imiquimod (IQ) is known as an agonist of Toll-like receptor 7 (TLR7) and is widely used to treat various infectious skin diseases." (PMID 22233604, 2012).
injury (1 paper, 2025). Damage inflicted on the body as the direct or indirect result of an external force, with or without disruption of structural continuity. "After skin injury, TLR-7 is activated by host-derived nucleic acids, stimulating plasmacytoid dendritic cells (pDCs) to produce type I interferons (IFNs), which are vital for early inflammation and re-epithelialization." (PMID 41465460, 2025).
intrahepatic cholangiocarcinoma (1 paper, 2022). A carcinoma that arises from the intrahepatic bile duct epithelium in any site of the intrahepatic biliary tree. "TLR7 was found in 80% of human intrahepatic cholangiocarcinoma (ICC), but not in any normal human bile duct epithelium." (PMID 36476317, 2022).
keloid (1 paper, 2021). An irregularly shaped, elevated mark on the skin caused by deposits of excessive amounts of collagen during wound healing. "By inhibiting the TGF-β1-SMAD signaling pathway and activating TLR7 or SMAD 7, keloid formation can be significantly reduced." (PMID 34359971, 2021).
keratinocyte carcinoma (1 paper, 2021). A skin cancer arising from the keratin-producing cells of the epidermis. "Similarly, we previously documented an adjuvant effect of AFL on topically applied immunotherapy, namely imiquimod, a Toll-like receptor 7-agonist immunotherapeutic drug that is commonly used for keratinocyte carcinoma treatment." (PMID 34944945, 2021).
keratitis (1 paper, 2014). A corneal disease that is characterized by inflammation of the cornea. "Upregulated mRNA levels for TLR 4, 7, 8, and 9 in human cornea with active keratitis and upregulated TLR7 expression in cornea with nonactive keratitis as compared to the normal cornea suggest the role of these receptors cells in the HSV-1 infection." (PMID 25276842, 2014).
Klebsiella pneumonia (1 paper, 2012). An pneumonia caused by infection with Klebsiella. "Analysis of cytokine responses of respiratory leukocytes after stimulation with Klebsiella pneumonia indicated reduced IFN-γ and TNF-α expression and increased IL-10 and IL-12p70 production after 7 day low dose skin TLR7 triggering." (PMID 22927956, 2012).
Knee osteoarthritis (1 paper, 2022). "Knee osteoarthritis (OA) is the most prevalent type of OA, and Toll-like receptor 7 (TLR7) may lead to the pathogenesis of OA." (PMID 35508687, 2022).
lacrimal gland disease (1 paper, 2020). "Through RNA sequencing studies, we identified genes and pathways up-regulated in lacrimal glands of wild-type NOD mice compared to TLR7-deficient NOD mice and compared this gene set to a set of genes up-regulated in lacrimal gland disease in a type I IFN-dependent manner." (PMID 33322152, 2020). "While the different IFN-dependencies in the sex-specific SS manifestations in NOD mice may explain the male-specific protection from lacrimal gland disease in Tlr7 KO mice, this does not explain the sex differences in T1D protection." (PMID 33322152, 2020).
laminopathy (1 paper, 2020). A rare genetic disorder caused by mutations in genes encoding proteins of the nuclear lamina. "In muscle tissue from laminopathy patients, TLR7 and TLR9 mRNA are significantly increased, and many muscle tissue-infiltrating CD68+ macrophages are TLR7 and TLR9 positive." (PMID 32580419, 2020).
latent infections (1 paper, 2020). "TLR7 agonists increase the anti-HIV-1 immune response, the activation of HIV-1 expression, and the inhibition of HIV-1 replication, which may help to treat latent infections." (PMID 32604797, 2020).
leishmaniasis (1 paper, 2014). Infectious disease that is transmitted through the bite of hematophagous female phlebotomine sand flies. "Most studies of TLRs in leishmaniasis have been done in the murine models, where expression of TLR2, TLR4, TLR7, TLR8 and TLR9 have been analyzed and related to disease outcome, together with other contributing factors such as Leishmania species and genetic background." (PMID 25397678, 2014).
malignant glioma (1 paper, 2023). A grade III or grade IV glioma arising from the central nervous system. "A recent study indicated that mechanisms of sensitizing malignant glioma cells lacking galectin-1 to NK killing might relate to a decrease in the release of miR-1983, which could activate endogenous toll-like receptor 7 (TLR7) in plasmacytoid DCs as well as conventional DCs as a ligand." (PMID 37047471, 2023).
mantle cell lymphoma (1 paper, 2014). Mantle cell lymphoma is a rare form of malignant non-Hodgkin lymphoma affecting B lymphocytes in the lymph nodes in a region called the ``mantle zone''. "In mantle cell lymphoma (MCL), TLR1, TLR4, TLR7, TLR9 and TLR10 exhibit significant mRNA levels, whereas TLR2, TLR3, TLR5 and TLR8 are negative." (PMID 25112836, 2014).
medulloblastoma (1 paper, 2023). A malignant, invasive embryonal neoplasm arising from the cerebellum. "Considering the prominent and contrasting expression profiles, TLR7 has been proposed as a prognostic factor of survival in pediatric medulloblastoma patients." (PMID 37822929, 2023). "Interestingly, TLR7, TLR8, and TLR9 genes were found to possess a differential expression pattern in most of the common pediatric medulloblastoma histological subtypes." (PMID 37822929, 2023).
meningococcal disease (1 paper, 2016). "Indeed, in the sera of mice immunized with Alum-TLR7 we measured higher SBA titers, a parameter that evaluate the functional activity of the antibodies and predicts vaccine effectiveness against meningococcal disease." (PMID 27439378, 2016).
mesothelioma (1 paper, 2022). A usually malignant and aggressive neoplasm of the mesothelium which is often associated with exposure to asbestos. "Moreover, the protective effect of CpG stimulation, and to a lesser extent of TLR3 and TLR7/8, and the role of IL-12 in this protection were confirmed in a model of early mesothelioma AB1 cell growth." (PMID 36714124, 2022).
metastatic colorectal cancer (1 paper, 2019). "In addition to this, polymorphism in the TLR7 gene have been suggested to predict the outcome of patients with metastatic colorectal cancer in response to chemotherapy." (PMID 31835892, 2019).
migraine (1 paper, 2024). "It highlights the cascade initiated by the binding of antiphospholipid antibodies (aPLs) to anionic phospholipids, the subsequent release of extracellular vesicles, and the activation of Toll-like receptors (TLR7 and TLR9), leading to neuroinflammation and migraine development." (PMID 39728754, 2024).
mononucleosis (1 paper, 2020). "In this study, we investigated whether CMV mononucleosis was associated with improper TLR functional responses and/or to the presence of SNPs within TLRs selected for their possible functional effects (TLR2 Arg753Gln; TLR3 Pro554Ser; TLR4 Asp299Gly; TLR7 Gln11Leu, and TLR9−1237 T/C)." (PMID 32850485, 2020).
myeloid malignancies (1 paper, 2025). "This suggests that TLR8 expression could potentially serve as a predictive biomarker of response to TLR7/8 agonists in myeloid malignancies." (PMID 40858756, 2025).
myxoma (1 paper, 2012). A benign soft tissue neoplasm characterized by the presence of spindle and stellate cells, lobulated growth pattern, and myxoid stroma formation. "Strikingly, WT vaccinia infection blocks type I IFN/TNF induction in response to myxoma, TLR9 agonist CpG, or TLR7 agonist imiquimod." (PMID 22606294, 2012). "In contrast, myxoma-induced type I IFN induction was abolished in MyD88−/−, or TLR9−/− pDCs, but modestly reduced in TLR7−/− pDCs." (PMID 22606294, 2012).
Nasal polyposis (1 paper, 2016). Polypoidal masses arising mainly from the mucous membranes of the nose and paranasal sinuses. "However, the TLR7/8 agonist R848 triggers the induction of IL-33 in healthy epithelium only (23.2 ± 6.17, p < 0.05) and not nasal polyposis epithelium (1.57 ± 0.38), despite the IL-6 and IL-8 induction levels being similar between those two groups." (PMID 27050744, 2016).
Newcastle disease (1 paper, 2021). A condition caused by infection by the Newcastle disease virus, which may be characterized by conjunctivitis, respiratory illness, and diarrhea. "In chicken bone marrow macrophage cell line HD11, TLR7 inhibited the replication of Newcastle disease." (PMID 34512716, 2021). "In Newcastle disease, a similar expression level of TLR3 and TLR7 is reported in chicken embryo fibroblasts and duck embryonic fibroblasts that activate host innate immune responses upon signaling cues received by pro-inflammatory cytokines and IFNs." (PMID 34512716, 2021).
non-alcoholic fatty liver disease (1 paper, 2016). "Based on this report, we investigated whether TLR7 has a pivotal role in non-alcoholic fatty liver disease (NAFLD)." (PMID 27279075, 2016).
Oral ulcer (1 paper, 2022). Erosion of the mucous mebrane of the mouth with local excavation of the surface, resulting from the sloughing of inflammatory necrotic tissue. "Also, TLR7-rs3853839 genotype CG and wild model were associated with oral ulcer (CC vs CG, P = 0.01, OR 0.25, 95% CI 0.09–0.74 and CC vs CG + GG, P = 0.04, OR 3.15, 95% CI 1.09–9.13)." (PMID 36439744, 2022).
otitis media (1 paper, 2016). Inflammation of the anatomical structures of the middle ear, which is most often caused by an infectious process. "There was a non-significant finding that the TLR7 major allele A, when present as homozygous, was connected to recurrent otitis media in females (p = 0.07), but this was not seen in males." (PMID 27498757, 2016).
plasmacytoma (1 paper, 2022). Plasmacytoma is a localized mass of neoplastic monoclonal plasma cells that represents approximately 5% of all plasma cell neoplasms. "In addition, TLR3 ligand Poly (I:C) and TLR7/8 ligand R848 had no preventive effect against plasmacytoma growth (p = 0.56 and 0.28, respectively)." (PMID 36714124, 2022).
post-infectious disorder (1 paper, 2023). A disorder that follows infection but is distinct from the infection itself and its usual manifestations. "Findings from disease network analysis TLR7 were linked to immune system disorders, cancer or benign tumors, infectious or post-infectious disorders, and integumentary system diseases, reflecting its widespread distribution and essential function in the human body." (PMID 37362864, 2023).
psychotic disorder (1 paper, 2015). An abnormal condition of the mind that involves a loss of contact with reality. "Indeed our psychosis module included several immune-related genes, including TLR7, which is part of a class of genes called toll-like receptors, whose molecules activate an inflammation response and have been shown to be elevated in peripheral blood of those with psychotic disorders." (PMID 26201030, 2015).
radiation pneumonitis (1 paper, 2025). Inflammation of the lung due to harmful effects of ionizing or non-ionizing radiation. "This implies that a gene dosage effect may be at play and points to an association between TLR7 and sex differences in radiation pneumonitis." (PMID 39808500, 2025). "Association between TLR7 and sex differences in development and treatment of radiation pneumonitis." (PMID 39808500, 2025).
respiratory depression (1 paper, 2023). A decrease in ventilation secondary to impaired signals from the central nervous system. "Formulation of the vaccine with a nucleolipid TLR7/8 agonist enhanced its immunogenicity and efficacy in preventing fentanyl-induced respiratory depression, analgesia, bradycardia, and self-administration in either rats or mini-pigs." (PMID 37488109, 2023).
Respiratory tract infection (1 paper, 2021). An infection of the upper or lower respiratory tract. "Probiotic treatment significantly upregulates the expressions of TLR7, MyD88, IRAK4, TRAF6, and NF-κB to alleviate FM1 influenza virus-induced respiratory tract infection." (PMID 33924002, 2021).
RSV bronchiolitis (1 paper, 2009). "For TLR7 and 9 there was a similar pattern of greatly increased neutrophil mRNA expression in preterm infants with RSV bronchiolitis compared with the other two groups." (PMID 19497921, 2009).
salivary gland disease (1 paper, 2020). "Moreover, TLR7 may provide a protective role in salivary gland disease in male NOD mice." (PMID 33322152, 2020). "TLR7 signaling is a well-established type I IFN-driving stimulus, which is in accordance with our findings of the requirement of TLR7 for male-specific lacrimal gland inflammation in NOD mice but not for female-specific salivary gland disease." (PMID 33322152, 2020).
scrapie (1 paper, 2024). A fatal disease of the nervous system in sheep and goats, characterized by pruritus, debility, and locomotor incoordination. "Previous studies have reported that TLR7 increased in the thalamus in FFI, and it mean inflammation might take part in pathogenesis of scrapie." (PMID 38698886, 2024).
Senile plaques (1 paper, 2024). Senile plaques are extracellular deposits of amyloid in the gray matter of the brain. "Additionally, other studies have demonstrated the increased expression of TLR2, TLR4, TLR5, TLR7, TLR9, and the co-receptor CD14 in microglial cells surrounding senile plaques in the brain tissues of patients with AD and AD mouse models." (PMID 38360834, 2024).
silicosis (1 paper, 2016). Silicosis is a respiratory disease caused by breathing in (inhaling) silica dust. "In this study, we also investigated whether or not the pharmacological modulation of TLR7 with TMX-306 could be used to reduce silicosis." (PMID 27014274, 2016).
skin infection (1 paper, 2019). An inflammatory process affecting the skin, caused by bacteria, viruses, parasites, or fungi. "Following VSV skin infection, TLR7−/− mice display significantly less VSV titers in the draining lymph nodes (dLN) and viral replication is attenuated in SCS macrophages." (PMID 30930901, 2019). "Intriguingly, how the TLR7/MyD88 pathway orchestrates VSV infection in dLN and subsequent type-I IFN responses after skin infection remains unresolved and warrants an in-depth investigation." (PMID 30930901, 2019). "By generating novel TLR7 floxed mice, we interrogate the impact of cell-specific TLR7 function in anti-viral immunity after VSV skin infection." (PMID 30930901, 2019).
sleep disorder (1 paper, 2025). A change from the patient's baseline sleeping pattern, in the hours slept and/or an alteration/dysfunction in the stages of sleep. "Future studies should focus on the role of BANK1 in mood and sleep disorders, aiming to identify other than TLR7 and TLR9 upstream regulators involved in this pathway." (PMID 41516251, 2025).
synovitis (1 paper, 2022). Inflammation of a synovial membrane. "We additionally dichotomized MRI-identified effusion-synovitis as none (WORSM 0) vs. any (WORSM 1–3) and investigated the relationship between the two SNPs on TLR7 and MRI-defined effusion-synovitis." (PMID 35508687, 2022).
synucleinopathies (1 paper, 2023). "Additionally, TLR7 inhibition has been shown to reduce the accumulation of αSyn in animal models of PD, suggesting that TLR7 may be a potential therapeutic target for the treatment of synucleinopathies." (PMID 37174631, 2023). "In fact, TLR7 activation can lead to the accumulation of αSyn in the brain and TLR9 might also be involved in the activation of microglia and the production of pro-inflammatory cytokines in synucleinopathies." (PMID 37174631, 2023).
syphilis (1 paper, 2012). A contagious bacterial infection caused by the spirochete Treponema pallidum. "In support of a similar role for phagosomal signaling in Tp-mediated induction of type I INFs, three endosomal TLRs (TLR7, 8 and 9), capable of sensing nucleic acids within phagosomes of macrophages and DCs, also were markedly up-regulated in syphilis lesions." (PMID 22816000, 2012).
thymoma (1 paper, 2017). A neoplasm arising from the epithelial cells of the thymus. "We also compared mRNA levels of TLR7 and TLR9, two endosomal-lysosomal receptors able to recognize bacterial or viral RNA and DNA and found significantly increased in EBV-positive hyperplastic MG thymuses, among normal thymuses, MG and non-MG thymomas." (PMID 29221139, 2017).
tonsillitis (1 paper, 2026). Inflammation of the tonsillar tissue. "Mononuclear cells isolated from palatine tonsils of patients with recurrent tonsillitis or immunoglobulin A (IgA) nephropathy were cultured with LF, TLR7, or TLR9 ligands." (PMID 41828658, 2026).
urothelial carcinoma (1 paper, 2018). A malignant neoplasm derived from the transitional epithelium of the urinary tract (urinary bladder, ureter, urethra, or renal pelvis). "As potential treatment options for urothelial carcinoma, the TLR-7 agonists TMX-101 and TMX-202 are subjects of research." (PMID 29767328, 2018). "TMX-101 and TMX-202 are formulations of toll-like receptor 7 (TLR-7) agonists, under investigation for the treatment of urothelial carcinoma." (PMID 29767328, 2018).
viral pneumonia (1 paper, 2018). Inflammation of the lung parenchyma that is caused by a viral infection. "In the present study, we find that OMT can significantly decrease the expressions of TLR3, TLR4, TLR7, MyD88, and TRAF6 genes after IAV infection, and we preliminarily speculate that OMT may inhibit IAV proliferation and IAV viral pneumonia via inhibiting TLRs signaling pathways." (PMID 29570670, 2018).